EGFR (epidermal growth factor receptor)
Diseases named in the same sentence as EGFR in open-access papers (continued):
Sharing a sentence is not in itself a finding about the gene and the disease.
gastric cancer (continued). "Further clinical studies will be needed to determine whether EGFR inhibitors reverse the resistance to irinotecan in patients with advanced gastric cancer." (PMID 21997136, 2011). "EGFR overexpression in gastric cancer commonly leads to radiation resistance." (PMID 21689422, 2011). "Therefore, in the present study, we utilized fluorescence in situ hybridization (FISH) to assess amplification of the ERBB2 and EGFR genes in gastric cancer patient samples." (PMID 21689422, 2011). "However, in gastric cancer, EGFR gene amplification only occurs in a subset of patients in the range of 2-9%." (PMID 22152101, 2011). "The combination treatment with an EGFR inhibitor and irinotecan might produce synergistic anti-tumour effects for irinotecan-refractory gastric cancer cells." (PMID 21997136, 2011). "Epidermal growth factor receptor is highly expressed in approximately one-third of advanced-stage gastric cancers, and the activation of EFGR may be involved in chemoresistance in solid tumours." (PMID 21997136, 2011). "Notably, advanced gastric cancer patients with EGFR expression in their tumours together with low serum levels of the ligands EGF and transforming growth factor-α showed better response in one study." (PMID 22152101, 2011). "Furthermore, a higher frequency of ERBB2 and EGFR gene amplification is present in gastric cancer patients with lymph node metastases." (PMID 21689422, 2011). "Similarly, overexpression of another receptor tyrosine kinase (RTK) EGFR, has been noted in gastric cancer and multiple trials of EGFR inhibitors in this cancer type are ongoing." (PMID 21781349, 2011). "Moreover, the correlation between EGFR/ERBB2 expression in gastric cancer and prognosis remains controversial." (PMID 21689422, 2011). "The combination treatment with an EGFR inhibitor and irinotecan might be a therapeutically promising approach for irinotecan-refractory gastric carcinomas." (PMID 21997136, 2011). "Epidermal growth factor receptor has been found to be overexpressed in gastric cancer." (PMID 20068568, 2010). "Epidermal growth factor receptor, the target of cetuximab, is overexpressed in gastric cancer." (PMID 20068568, 2010). "The prognostic and predictive roles of EGFR expression in gastric cancer thus remain controversial." (PMID 19259093, 2009). "Low EGFR expression might be a predictive marker for relapse in curative resected stage III–IV (M0) gastric cancer patients who received adjuvant FP chemotherapy." (PMID 19259093, 2009). "Differences in EGFR expression among these studies may also be attributed to the lack of an established immunohistochemical scoring system commonly used to evaluate gastric cancer." (PMID 19259093, 2009). "EGFR mutations in primary gastric carcinoma or gastric cancer cell lines were never reported; nevertheless we recently showed that hereditary diffuse gastric cancer associated E-cadherin germline missense mutations lead to increased EGFR activity." (PMID 18199332, 2008). "EGFR overexpression has been described in many human tumours including gastric cancer." (PMID 18199332, 2008). "The data from our study suggest that chromosome 7 polysomy may be responsible for increased EGFR gene copy number in gastric carcinomas, and that HER2 gene amplification may be the major reason for HER2 protein overexpression." (PMID 19061514, 2008). "Four gastric carcinomas showed balanced polysomy or EGFR gene amplification." (PMID 18199332, 2008). "More recently it has been reported that, in human MKN7 gastric cancer cells, HRGβ1 can also circumvent the antiproliferative action of the selective EGFR-TKI CGP59326 through promotion of erbB3/erbB2 heterodimerization and activation of the PI3K signalling pathway." (PMID 17686159, 2007). "There may be other regulatory mechanisms for EGFR in gastric cancer." (PMID 39838173, 2025). "In addition, EGFR targeting therapies produced little effect in gastric cancer patients." (PMID 39838173, 2025).
gastric cancer (continued). "It is also reported that the growth of gastric cancer cells in mice is significantly inhibited by treatment with 25 μg/mL of taraxasterol for 16 days, and a mechanism study demonstrates that taraxasterol inhibited the growth of gastric cancer cells in mice by inhibition of EGFR/AKT1 signaling." (PMID 41374059, 2025). "Indeed, we could already demonstrate an HDACi-mediated downregulation of HER2 in gastric carcinoma, suggesting that this could at least contribute to a compensatory EGFR upregulation." (PMID 39864337, 2025). "EGFR methylation might promote the transformation of chronic gastritis into gastric carcinoma." (PMID 37964307, 2023). "In unselected gastric cancer (GC) patients with advanced disease, trials combining chemotherapy and an anti-EGFR monoclonal antibody have been largely unsuccessful." (PMID 35289315, 2022). "Thus, EGFR/HER2-targeted NIR-PIT is a promising approach for gastric cancer patients." (PMID 35453596, 2022). "Moreover, EGFR in exosomes secreted from gastric cancer cells can be delivered into the pre-metastatic liver and is integrated on the plasma membrane of liver stromal cells, including Kupffer cells and hStCs, which effectively facilitates the landing and proliferation of metastatic cancer cells." (PMID 35006432, 2021). "In another study, epidermal growth factor receptor (EGFR) on EVs derived from gastric cancer (GC) cells can be transferred to the liver and internalized by liver stromal cells." (PMID 34295457, 2021). "In the treatment of MDR gastric cancer cells, we speculate that miR-1323 may be a functional target of elemene to reverse drug resistance, and elemene inhibited miR-1323, which in turn upregulated Cbl-b expression and then inhibited the EGFR-ERK/Akt pathway." (PMID 34641334, 2021). "Therefore, we examined whether CD148 affected EGFR and downstream signaling pathways in gastric cancer." (PMID 32201537, 2020). "Therefore, we sought to identify potential molecular or genomic determinants that could aid in design of effective EGFR targeted therapy, specifically utilizing gefitinib, in treating gastric cancer patients." (PMID 32070411, 2020). "Therefore, increased oxidative stress might facilitate the progression of gastric cancer via EGFR activation." (PMID 31491956, 2019). "Furthermore, we found that EGF stimulated AGS cell migration and knockdown of WWTR1 impairs both EGF-stimulated and EGF-independent AGS cell migration, suggesting that WWTR1 might mediate both EGFR-dependent and –independent gastric cancer cell migration." (PMID 30976198, 2019). "Indeed, a panel of double EGFR markers may be more efficient in comparison with all of the regular single based markers in gastric cancer cases." (PMID 30621788, 2019). "Moreover, NOX4 expression is positively correlated with EGFR expression, which might convert them as promising biomarkers of gastric cancer for the clinics." (PMID 30237423, 2018). "miR-520b/e could regulate cell proliferation and migration by targeting EGFR in gastric cancer." (PMID 29103082, 2018). "Although MSI-H gastric cancers are hyper-mutated, MSS gastric cancers also possess a high frequency of genetic alterations such as CDH1, RHOA, HER2, EGFR, VEGFR, MET, and FGFR2, all of which may directly or indirectly affect the MAPK and PI3K/Akt survival pathways." (PMID 29137273, 2017).
gastric cancer (continued). "We examined 106 primary resected gastric cancer patient tissues in a tissue microarray and correlated native-occurring fragments with clinical endpoints, therapeutic targets such as epidermal growth factor receptor (EGFR) and HER2/neu expressions and the proliferation marker MIB1." (PMID 28978092, 2017). "Thus, we have investigated whether gastric cancer cells stimulation with an agonist of GPBAR1 results in the phosphorylation of the EGFR." (PMID 27409173, 2016). "However, in future, patients with gastric cancer showing EGFR overexpression might benefit from treatment with nimotuzumab." (PMID 25185971, 2015). "Additionally, our results indicated that EGFR, contribute to the downstream regulation of Linc00152 in gastric cancer which may serve as potential targets for therapy in the future." (PMID 26538117, 2015). "The frequency of EGFR amplification may be lower in European and North American populations (6.5 -12.5 %) when compared to studies in Asian patients (7-49 %), implying a significant ethnic component to EGFR dysregulation in esophago-gastric cancer." (PMID 26478746, 2015). "Consequently the methylation levels of EGFR could be considered as a potential epigenetic biomarker for gastric cancer status and progression." (PMID 25959250, 2015). "However, we found that PKM2 could also regulate the activity of the EGF/EGFR signaling pathway in gastric cancer cells." (PMID 23840737, 2013). "Consequently, EGFR was selected as the target in gastric cancer cells in the present study." (PMID 23833649, 2013). "Thus, mechanisms that regulate EGFR signaling could contribute to 5-FU sensitivity in gastric cancer." (PMID 24351824, 2013). "Indeed, a recent study has also shown that genes located adjacent to EGFR at 7p11 or SMAD4 at 18q21 were in close association with one another and may play a role in the pathogenesis of advanced gastric carcinoma." (PMID 22559327, 2012). "Therefore, the blockage of the EGFR signalling in combination with SN38 may contribute to anti-tumour effects against irinotecan-refractory gastric cancer." (PMID 21997136, 2011). "Therefore, EGFR-targeted radiosensitization treatments may have important clinical value for treatment of gastric cancer." (PMID 21689422, 2011). "Co-expression of ERBB2 and EGFR may have synergistic effects on the progression of gastric cancer." (PMID 21689422, 2011). "Aside from HER2, EGFR may also be a promising therapeutic target in gastric cancer." (PMID 22152101, 2011). "Finally, we showed that the signaling pathways that responded to PAR1 activation involving the activation of NF-κB and transactivation of EGFR, which might be stimulated by TN-C, resulted in an increase in gastric cancer cell proliferation and invasion." (PMID 20723226, 2010). "Receptors such as the epidermal growth factor receptor (EGFR) and human epidermal growth factor receptor 2 (HER2) are well-established drivers in lung, breast, and gastric cancers." (PMID 41608666, 2026). "Ephrin A1 binds to and activates EGFR to induce epithelial-mesenchymal transition (EMT) and promote metastasis of gastric cancer cells." (PMID 39838173, 2025). "Pyrotinib, an irreversible dual EGFR/HER2 tyrosine kinase inhibitor, has shown clinical efficacy in HER2-driven malignancies, but its potential role in EGFR-high copy number gastric cancer remains to be investigated." (PMID 40830980, 2025). "BBR also combats stomach cancer by inhibiting STAT3 activation and reducing the phosphorylation of the epidermal growth factor receptor (EGFR)." (PMID 40110809, 2025). "In esophageal and gastric cancers, targets such as HER2 (NCT02713984), EGFR, CEA (NCT02349724), MSLN (NCT03747965), CLDN18.2 (NCT05472857), and NKG2D have shown effective antitumor effects in preclinical and early clinical trials." (PMID 40909948, 2025). "In a clinical trial targeting both EGFR and MET, amivantamab achieved a disease control rate of 26.1% in patients with gastric cancer and gastroesophageal junction cancer." (PMID 41361128, 2025).
gastric cancer (continued). "In gastric cancer, CYTOR is up-regulated and can promote tumor growth through the epidermal growth factor receptor (EGFR)-mediated PI3K/PKB pathway." (PMID 40308216, 2025). "In gastric cancer cells, oxymatrine decreased the proliferation and invasion of gastric cells by inhibiting the EGFR/Cyclin D1/CDK4/6, EGFR/Akt, and MEK-1/ERK1/2/MMP2 pathways by inhibiting EGFRp-Tyr845." (PMID 40728967, 2025). "Although we demonstrated Ephrin A1 functioned as the ligand of EGFR to induce EMT and metastasis in gastric cancer cells in this study, Ephrin A1 was reported to be highly expressed in multiple tumors and EGFR was an important target in many cancers." (PMID 39838173, 2025). "In contrast, we observed an increase in EGFR mRNA levels but a decrease in EGFR protein levels in 2D cultures of NCI-N87 cells, emphasizing the heterogeneity within gastric cancer cell lines." (PMID 39864337, 2025). "In gastric cancer, key examples include HER2-targeted, EGFR-targeted, and VEGF/VEGFR-targeted agents." (PMID 40458806, 2025). "The results showed that TS inhibited the growth of gastric cancer by down-regulating the expression of EGFR and AKT1 in cancer cells and inhibiting the EGFR/AKT1 signaling pathway." (PMID 39338278, 2024). "In gastric cancer, CMTM3 promotes the degradation of EGFR to impede tumor metastasis, indicating that knocking out the CMTM3 gene can be a potential therapy for gastric cancer." (PMID 38223763, 2024). "Among them is EGFR, the expression product of the proto-oncogene HER-1, a key oncogene in gastric cancer, whose receptor tyrosine kinase activity triggers key signaling pathways for tumor cell growth and survival." (PMID 38660675, 2024). "CMTM3 affects EMT progression by inhibiting the EGFR/STAT3 signaling pathway, thereby inhibiting the development of tumorigenesis in chordoma and gastric cancer." (PMID 38223763, 2024). "DARPP-32 can enhance the interaction between EGFR and ERBB3, thereby activating the phosphatidylinositol 3-kinase (PI3K)-AKT signaling pathway and promoting resistance to gefitinib in gastric cancer cells." (PMID 39309860, 2024). "Several signaling pathways, including Notch in gastric cancer, JNK/STAT3 in hepatocytes, and EGFR in oral cancer, regulate autophagy and support CSC survival." (PMID 39456967, 2024). "Upon TRIM11 silencing in gastric cancer cells AGS and SGC-7901, both EGFR and AKT showed decreased expression levels, indicating that it plays a role in the activation of the AKT signaling pathway." (PMID 39768197, 2024). "For example, we have previously shown that using linear mixed models, EGFR gene expression was identified as the best single-gene biomarker for predicting the efficacy of Erbitux, an EGFR mAb, on patient-derived xenograft (PDX) models of gastric cancer." (PMID 39099194, 2024). "The gastric cancer genome is characterized by focal amplification of oncogenes, including receptor tyrosine kinases, such as ERBB2 (HER2), EGFR, ERBB3, VEGF-A, KRAS/NRAS, MET, JAK2, and PD-L1/PD-L2." (PMID 38733489, 2024). "Consistent with other findings linking MET and EGFR oncogenic signaling, the resistance to MET inhibitors in lung and stomach carcinoma cells was accounted by NRP1-dependent EGFR upregulation." (PMID 39769452, 2024). "Among them, lapatinib is a dual inhibitor targeting EGFR and HER-2, which demonstrated possibilities in preclinical studies of HER-2-positive patients with advanced gastric cancer." (PMID 38137387, 2023). "EGFR signaling has been extensively studied in the context of gastric cancers with several EGF receptors, such as HER2 (Erbb2) and EGFR, which are found to be frequently overexpressed due to copy number amplification." (PMID 37386010, 2023). "EGFR and HER2 are the most recognized tyrosine kinase receptors in gastric cancer, while overexpression of other recognized tyrosine kinase receptors in gastric cancers includes fibroblast growth factor receptor 2 (FGFR2) and MET." (PMID 38186572, 2023).
gastric cancer (continued). "Drugs targeting human epidermal growth factor receptor-2 (HER-2), epidermal growth factor receptor (EGFR), vascular endothelial growth factor (VEGF) have provided gastric cancer patients with better survival rates." (PMID 37208608, 2023). "A range of mutations within the PIK3CA gene and amplification of receptor tyrosine kinase genes such as EGFR and HER2 were detected in the analyzed cases of gastric cancer." (PMID 37894443, 2023). "β-Elemicene can inhibit the peritoneal metastasis of gastric cancer by inhibiting FAK activation, as well as reverse multidrug chemoresistance by modulating the miR-1323/Cbl-b/EGFR pathway, in addition to sensitizing chemotherapeutic agents." (PMID 37730658, 2023). "Consistently, gastric cancer (GC) cell‐derived exosomal epidermal growth factor receptor (EGFR) can integrate with liver stromal cells and can effectively activate HGFs by directly targeting miR‐26a/b, preparing fertile ‘soil’ for future gastric cell metastasis to the liver." (PMID 36941028, 2023). "Several anoikis resistance related signal pathways have been reported in GC, including RhoA pathway, Wnt/β-catenin signaling pathway and EGFR signaling pathway, and these pathways promote angiogenesis, lymph node metastasis and peritoneal metastasis of gastric cancer cells." (PMID 36925640, 2023). "In recent years, therapeutics targeting molecules such as EGFR, HER-2, HER3, CLDN18.2, Mucin 1 have shown a degree of efficacy in managing progressive gastric cancer." (PMID 37305567, 2023). "The subsequent investigation verified CD24’s inhibition of EGFR internalisation and degradation via RhoA in SGC-7901 and BGC-823 gastric cancer cell lines." (PMID 38137380, 2023). "Dual inhibition strategies targeting both EGFR and HER2 have produced encouraging and promising outcomes and therefore is crucial to investigate them for benefiting patients with gastric cancers." (PMID 38186572, 2023). "In multiple studies, the EGFR is a substrate of USP8 deubiquitination, while USP8 has been shown to enhance gastric cancer cell proliferation and metastasis via the PI3K/AKT signaling pathway." (PMID 36338727, 2022). "We have shown in previous studies that the kinase activity of EGFR and HER2 in the gastric cancer cell lines NCI-N87, MKN1 and MKN7 is selectively inhibited by trastuzumab and afatinib." (PMID 35264144, 2022). "In gastric cancer cells, CD24 positively regulates the expression of EGFR, supporting the EGFR-PI3K/Akt and EGFR-ERK signaling pathway to suppress EGFR internalization and degradation in a Rho-A related signaling axis." (PMID 36231025, 2022). "Six out of the 13 PDOs contained an EGFR or HER2 overexpression, frequently found in gastric cancer, or pathogenic mutations in downstream members of the RTK/MAPK pathway (Table EV1)." (PMID 35993110, 2022). "At present, the therapeutic targets of gastric cancer mainly include HER-2, EGFR, PI3K, mTOR and c-Met, etc., and targeted drugs targeting these receptors and kinases have achieved certain results in the clinical application of gastric cancer treatment." (PMID 36465346, 2022). "Through a CRISPR screen implemented in gastric cancer cell line, ILK, CSK and EGFR pathways have been identified as critical roles in the resistance to FGFR inhibitor." (PMID 35372044, 2022). "Others have been reported to have good potential to be prognostic biomarkers for CRC (CDKN1A, CDKN1B), stomach cancer (MMP2,) and esophageal cancer (EGFR, PIK3CA,)." (PMID 35681633, 2022). "Low, or the absence, of correlation between EGFR dependency and expression is shown for CBS and SRM genes in rhabdoid cancer, for the MTR gene in gastric cancer and for the SRM gene in rhabdoid and neuroblastoma cancer cells." (PMID 36361596, 2022). "When we assessed the expression status of individual gastric cancer oncogenes (e.g., CEACAM6, EGFR, MET, CCND1, and KRAS) among the tumor epithelial clusters, the EpiInt1 tumor epithelial cluster exhibited the largest increase." (PMID 34642171, 2022).